SNRPN (small nuclear ribonucleoprotein polypeptide N)
Diseases named in the same sentence as SNRPN in open-access papers (continued):
Sharing a sentence is not in itself a finding about the gene and the disease.
cancer (continued). "Also, the direction of changes in these genes is mostly hypermethylation, although there are some genes with hypomethylation in cancers, such as SNRPN (5/22) and H19 (5/22)." (PMID 26338779, 2015). "Numerous studies concerning the methylation of the SNRPN gene in cancer have been published." (PMID 25571951, 2015). "The early replicating SNRPN allele was not randomly distributed between the two chromosome-15s in either the informative (heterozygous) samples derived from non-cancer cases or those derived from the informative cancer cases." (PMID 19109880, 2008). "In addition, the CEN15 alleles, which normally replicate synchronously, as seen here in the cells of the non-cancer patients, replicated highly asynchronously in the cells of the cancer patients, similar (P > 0.30) to the SNRPN in the cells of cancer-free patients." (PMID 19109880, 2008). "In addition, the diagnostic models developed from the BAE, MAE, and TE measurements of the imprinted gene panel GNAS, GRB10, and SNRPN could provide important predictive information which are useful in early-stage cancer detection and personalized cancer management." (PMID 32448196, 2020). "For example, in cancer, GNAS, BCR and SNRPN showed both expression downregulation and CNV losses, while for HM13, gains were linked with overexpression." (PMID 30297886, 2018). "The abnormal SD values for SNRPN and CEN15 in the cells of the cancer patients were shifted toward normal in the presence of AZA, a methylation-blocking agent." (PMID 19109880, 2008). "Targeted inhibition of expression SNRPN, WNK3 and FAM3B may therefore constitute a potential therapeutic strategy for HCC and more generally for other cancers." (PMID 34006907, 2021). "In order to find useful and efficient cancer biomarkers for clinical applications, we generated the ROC curves for the GNAS, GRB10, SNRPN, IGF2, and IGF2R imprinted genes using the individual BAE, MAE, and TE measurements for all the different cancer types combined." (PMID 32448196, 2020). "We conclude that only a limited set of imprinted genes, including IGF2 and SNRPN, may be useful for LOI cancer biomarker studies." (PMID 21042416, 2010). "PPM1A, SNRPN, RAB5B, and CAPG were also reported to be related to cancer." (PMID 18237428, 2008).
tumor (8 papers, 2003 to 2024). "Clinical pathological factor analysis demonstrated that higher expression of SNRPN was significantly associated with larger tumor size, location of the tumor on the left-sided colon, neural invasion, and distant metastasis." (PMID 33224876, 2020). "Both in vitro and in vivo experiments confirmed that high expression of SNRPN was associated with tumor proliferation, cell cycle, and metastasis." (PMID 33224876, 2020). "The scores of IHC in tumor tissues were significantly higher than in normal tissues (P < 0.001), suggesting the accumulated expression of SNRPN in CRC tissues." (PMID 33224876, 2020). "In our previous study, we suggested that the varying degrees of hypomethylation of H19DMR and hypermethylation of SNRPN and KvDMR are dependent on the stage of oogenesis from which each tumor arises." (PMID 28288660, 2017). "Analysis of the data from eight papillary thyroid carcinoma (PTC) tumor samples revealed that amplifications of SNRPN occurred solely in tumors with a wild type B-type Raf kinase (BRAF)." (PMID 25571951, 2015). "Analysis of the data from eight PTC tumor samples revealed that amplifications of SNRPN occurred solely in tumors with a wild-type BRAF." (PMID 25571951, 2015). "Additionally, clinical and pathological data show that increased SNRPN expression is correlated with larger tumor size, tumor location on the left-sided colon, neural invasion, and distant metastasis." (PMID 33224876, 2020).
neurodevelopmental disorder (3 papers, 2009 to 2022). A behavioral and cognitive disorder with onset during the developmental period that involves impaired or aberrant development of intellectual, motor, or social functions. "The bicistronic gene SNURF-SNRPN, referred here as SNRPN, has been extensively studied in mice and humans due to the correlation between disorders within the SNRPN differentially methylated region (DMR) and the pathogenesis of neurodevelopmental disorders known as Prader-Willi Angelman syndrome." (PMID 19200381, 2009).
neurological disorder (2 papers, 2012 to 2014). "AS is a neurological disorder that is caused by loss of maternal-specific methylation at the small nuclear ribonucleoprotein N (SNRPN) ICR." (PMID 22798963, 2012).
brain disorder (1 paper, 2016). A disease affecting the brain or part of the brain. "This evidence indicates that Nr4a1 is responsible for defects caused by SNRPN knockdown and that pharmacological inhibition of Nr4a1 is a potential therapeutic target for SNRPN-related brain disorders." (PMID 27430727, 2016).
heart disease (1 paper, 2023). "However, the role of SNRPN in heart disease remains largely unknown." (PMID 37932671, 2023).
SNRPN also shares sentences with these, for which no sentence is quoted: Beckwith-Wiedemann syndrome (2 papers); infection (2); Intellectual disability (2); thyroid cancer (2); autoimmune disease (1); Bardet-Biedl syndrome (1); Biotin deficiency (1); central precocious puberty 2 (1); congenital heart disease (1); cryptorchidism (1); DiGeorge syndrome (1); epilepsy (1); genetic disorder (1); gestational trophoblastic diseases (1); hypogonadism (1); Kabuki syndrome (1); Koolen-de Vries syndrome (1); lymphoma (1); mental retardation, X-linked syndromic, Lubs type (1); microcephaly (1); mixed connective tissue disease (1); myelodysplastic syndrome (1); nephritis (1); neuroblastoma (1); neurofibromatosis (1); Noonan syndrome (1); pituitary hormone deficiency (1); prediabetes (1); preeclampsia (1); psychosis (1).
A further 10 diseases each share a sentence with SNRPN in 1 paper.